TREM2 (triggering receptor expressed on myeloid cells 2)
Diseases named in the same sentence as TREM2 in open-access papers (continued):
Sharing a sentence is not in itself a finding about the gene and the disease.
Nasu-Hakola disease (continued). "For example, TREM2, an established AD risk factor that is primarily expressed in immune cells, is also the causative gene of Nasu-Hakola disease, an early-onset subcortical dementia that presents with white matter demyelination." (PMID 29110684, 2017). "A genetic mutation of TREM2 causes Nasu-Hakola disease and increases the risk of Alzheimer’s or Parkinson’s diseases." (PMID 28592261, 2017). "Autosomal recessive mutations of TREM2 such as Y38C and T66M lead to Nasu-Hakola disease characterized by bone cysts and dementia, believed to arise through loss of function." (PMID 29273078, 2017). "A different set of mutations in the gene for TREM2 can cause a more severe degenerative brain disease known as Nasu-Hakola disease in much younger people." (PMID 27995897, 2016). "Mutations in either TREM2 or DAP12 can cause polycystic lipomembranous osteodysplasia with sclerosing leukoencephalopathy (PLOSL or Nasu-Hakola disease), which is also characterized by presenile dementia in homozygous carriers." (PMID 26792193, 2016). "Mutations causing Alzheimer’s and Nasu-Hakola disease result in the production of mutant TREM2 proteins that differ from the normal protein by only a single amino acid." (PMID 27995897, 2016). "Further experiments examined how these mutations alter the properties of TREM2, revealing that mutations linked to Nasu-Hakola disease affect the ability of TREM2 to fold correctly and how stable its final shape is." (PMID 27995897, 2016). "This is suggested by the observation that TREM2 myeloid cell receptor dysfunction is implicated in Nasu-Hakola disease, a pathological condition that shares similar phenotypic abnormalities with RTT." (PMID 25107477, 2014). "Previously, mutations in TREM2 have been associated with Nasu-Hakola disease (aka polycystic lipomembranous osteodysplasia with sclerosing leukoencephalopathy, PLOSL)." (PMID 24829845, 2014). "Triggering receptor expressed on myeloid cells 2 (TREM2) homozygous mutations cause Nasu-Hakola disease, an early-onset recessive form of dementia preceded by bone cysts and fractures." (PMID 23870839, 2013). "In humans, congenital natural polymorphisms that cause loss of function mutations in either TREM2 or DAP12 result in Nasu-Hakola disease, which is characterized by late-onset demyelination in the CNS and osteopetrosis." (PMID 24058676, 2013). "Biallelic (both alleles carry a variant, homozygous or compound heterozygous) loss-of-function variants in either TYROBP or TREM2 cause Nasu-Hakola disease (NHD) known also as polycystic lipomembranous osteodysplasia with sclerosing leukoencephalopathy (PLOSL)." (PMID 40301889, 2025). "In humans, TREM2 is essential for maintaining normal brain homeostasis, and TREM2 mutations resulting in loss of function are associated with a distinct neurodegenerative condition, Nasu-Hakola disease." (PMID 38711159, 2024). "While TREM2 mutations causing total loss of function are closely linked to frontotemporal lobe dementia and Nasu-Hakola disease, AD-associated TREM2 mutations (such as R47H and R62H) are believed to cause partial loss of operation because they occur within the ligand-binding domain." (PMID 38249960, 2023). "In this study, fibroblasts were acquired from a patient either homozygous for the TREM2 p.T66M mutation or the TREM2 p.w50C mutation, both of which are missense mutations known to cause frontotemporal dementia-like syndrome and Nasu-Hakola disease, respectively." (PMID 37626736, 2023). "Loss of a functional Trem2 signaling pathway has been demonstrated as the genetic cause of Nasu-Hakola disease, which is characterized by early onset cognitive dementia, suggesting that microglial proper functioning during development is crucial for the process of brain development." (PMID 37252188, 2023).
Nasu-Hakola disease (continued). "However, the loss of functions in TREM2 in humans resulted in a severe form of dementia with bone cystic lesions known as Nasu-Hakola disease (NHD), a lethal form of progressive, early onset dementia." (PMID 33841415, 2021). "Although complete loss-of-function mutations in TREM2 are most strongly linked to Nasu-Hakola disease and frontotemporal dementia, AD-associated TREM2 mutations such as R47H and R62H occur within the ligand-binding domain and are thought to confer a partial loss of function." (PMID 33097708, 2020). "Furthermore, homozygous loss-of-function mutations in TREM2 are sufficient to cause Nasu-Hakola disease (NHD) and FTD-like syndrome." (PMID 30630532, 2019). "Four participants with AD carried the TREM2 rs104894002 (p.Q33X) high-impact mutation that, in homozygous form, causes Nasu-Hakola disease, a rare disorder characterized by early-onset dementia and multifocal bone cysts, suggesting an intermediate inheritance model for the mutation." (PMID 30924900, 2019). "Moreover, a rare mutation of human TREM2 (R47H) determines a high risk for developing AD and Nasu-Hakola disease, a disorder characterized by dementia, and amyloid plaque deposition is caused by genetic mutation of TREM2 or DAP12 genes." (PMID 31427930, 2019). "We used stem cell-derived microglia to study the consequences of missense mutations in the microglial-expressed protein triggering receptor expressed on myeloid cells 2 (TREM2), which are causal for frontotemporal dementia-like syndrome and Nasu-Hakola disease." (PMID 29606617, 2018). "While seemingly unrelated to PSP, a curious number of neurodegeneration-related genes are also involved in bone diseases (e.g. TREM2, which has been linked to AD and Nasu-Hakola disease, and VCP, linked to amyotrophic lateral sclerosis and Paget’s disease of bone)." (PMID 30089514, 2018). "In this sense, deficiencies on key genes for the microglial survival and/or proliferation (such as CSF1R or TREM2) are associated with rare hereditary neurodegenerative diseases, such as adult-onset leukoencephalopathy with axonal spheroids or Nasu-Hakola disease (respectively)." (PMID 29867449, 2018). "In the previous studies, it was found that the TREM2 R47H variant had a slight difference in N-glycosylation of the complex oligosaccharide compared to the Y38C and T66M variants, which are associated with Nasu-Hakola disease (NHD)." (PMID 29655369, 2018). "Clinical observations have shown the involvement of TREM2 in Nasu-Hakola disease (see Role of Microglia in Neurodevelopmental Disease), and recently, TREM2 mutations have been associated with an increased risk of developing amyotrophic lateral sclerosis, frontotemporal dementia (FTD) and AD." (PMID 28674485, 2017). "Interestingly, homozygous mutations in TREM2 have been shown to cause Nasu-Hakola disease and FTD, while the heterozygous R47H variant is associated with an increased risk for development of AD." (PMID 26792193, 2016). "Loss-of-function mutations in the gene encoding TREM2 or the adaptor protein through which it signals (DAP12) results in Nasu-Hakola disease, characterized by bone cysts and progressive encephalopathy and neurodegeneration that culminates in cortical atrophy and early-onset dementia." (PMID 25107477, 2014). "The critical role of TREM2 for neuronal health is highlighted by patients with autosomal recessive disorder with near complete loss of TREM2 function called polycystic lipomembranous osteodysplasia with sclerosing leukoencephalopathy (PLOSL or Nasu Hakola disease)." (PMID 24223593, 2013). "In humans, the loss-of-function of TREM2 or its coreceptor DAP12 is responsible for the recessively inherited Nasu-Hakola disease (also known as Polycystic lipomembranous osteodysplasia with sclerosing leukoencephalopathy; PLOSL), characterized by an early onset dementia associated with bone cysts." (PMID 23977213, 2013).
Nasu-Hakola disease (continued). "Interestingly, loss-of-function mutations of DAP12 or TREM2 both lead to a chronic neurodegenerative disease called Nasu-Hakola or polycystic lipomembranous osteodysplasia with sclerosing leukoencephalopathy (PLOSL), an autosomal recessive inherited disease." (PMID 20721346, 2010). "Nasu-Hakola disease (NHD) is a rare autosomal recessive disorder caused by mutations in the TYROBP or TREM2 genes." (PMID 41510405, 2025). "Homozygous variants in TREM2 are linked to the onset of Nasu-Hakola disease (NHD), a rare disorder characterized by early-onset dementia, demyelination, and bone cysts." (PMID 41168805, 2025). "Rare variants of TREM2 are associated with the occurrence of Alzheimer’s disease and Nasu-Hakola disease (NHD), and other neurological diseases, including PLOSL, frontotemporal dementia, and Parkinson’s disease." (PMID 34356130, 2021). "Whereas heterozygous variants in TREM2 are associated with AD, homozygous variants in TREM2 or its binding partner DAP12/TYROBP cause polycystic lipomembranous osteodysplasia with sclerosing leukoencephalopathy (PLOSL), also known as Nasu-Hakola disease (NHD)." (PMID 33422057, 2021). "Null mutations in TREM2 is a cause of Nasu-Hakola disease (NHD), a rare autosomal recessive brain disorder characterized by frontal lobe syndrome, early-onset dementia, and bone cysts." (PMID 33557250, 2021). "The mechanism by which biallelic loss-of-function mutations in the same gene TREM2, are pathogenic for the very rare Nasu-Hakola disease (NHD), or polycystic lipomembranous osteodysplasia with sclerosing leukoencephalopathy, poses an interesting conundrum." (PMID 34149605, 2021). "Human beings with a loss function of either TREM2 or DAP12 develop an inflammatory neurodegenerative disease—Nasu-Hakola disease (NHD), leading to death in the fourth or fifth decade of life." (PMID 35082781, 2021). "Nasu-Hakola disease (NHD), a rare genetic disease presenting with early-onset dementia, is linked to mutations in TREM2 that prevent surface expression of mature protein." (PMID 33198789, 2020). "Furthermore, the TREM2 variants Y38C and T66M, linked with the early-onset disease Nasu-Hakola disease (NHD) display differences in the N-glycosylation profile, but varies from the profile seen within the R47H variant, potentially explaining the late-onset in AD versus the early-onset seen in NHD." (PMID 33519371, 2020). "Loss-of-function mutations in TREM2 cause Nasu-Hakola disease (NHD), a rare genetic disease characterized by early-onset dementia with leukoencephalopathy and bone cysts." (PMID 29720600, 2018). "Homozygous missense mutations of TREM2 including Y38C or T66 M have been identified to be associated with Nasu-Hakola disease (NHD)." (PMID 29587871, 2018). "Homozygous loss of function mutations in TREM2 cause a rare autosomal recessive disease known as polycystic lipomembranous osteodysplasia with sclerosing leukoencephalopathy (PLOSL), or Nasu-Hakola disease." (PMID 23800361, 2013). "In the brain TREM2 is exclusively expressed on microglia, and homozygous mutations in TREM2 or its signaling partner DAP12 cause an early onset dementia known as Nasu-Hakola disease." (PMID 40770764, 2025). "Biallelic loss-of-function mutations in TREM2 or TYROBP (encoding its cytoplasmic adaptor molecule, also known as DAP12) cause Nasu-Hakola disease, also known as polycystic lipomembranous osteodysplasia with sclerosing leukoencephalopathy (PLOSL)." (PMID 40448228, 2025). "Recent studies have indicated that Trem2/Dap12 receptor complex is associated with Nasu-Hakola disease (NHD), where the abnormal expression leads to the activation and proliferation of microglia in the brains of patients, impairing microglial function and exacerbating cognitive decline." (PMID 40234956, 2025).
Nasu-Hakola disease (continued). "TREM2 loss-of-function mutations lead to significant lysosomal dysfunction and downregulated expression of genes involved in lipid metabolism in induced pluripotent stem cell (iPSC)-derived microglia from patients with Nasu-Hakola disease (NHD)." (PMID 40083551, 2025). "Meanwhile, recent studies have emphasized the importance of TREM2 and neuroinflammation in neurodegenerative diseases such as AD and Nasu-Hakola disease." (PMID 39159814, 2024). "Although TREM2 and TYROBP mutations are causative for Nasu-Hakola disease and increase the risk of AD, the link between these two dementias is still unclear." (PMID 36002854, 2022). "However, few studies have focused on the deleterious roles of Nasu-Hakola disease (NHD) associated TREM2 variants." (PMID 32107424, 2020). "Expression of the AD-associated R47H variant and Nasu-Hakola disease (NHD)-associated TREM2 mutants Y38C also strongly reduced the phagocytic activity of TREM2 in HEK293 cells mimicking previous observations in microglial cells expressing TREM2 mutations." (PMID 31649511, 2019). "For example, TREM2 and DAP12 are selectively expressed in CNS microglia and their mutations were linked to Nasu-Hakola disease (NHD), a condition that results in dementia." (PMID 31426845, 2019). "Interestingly, loss-of-function mutations of TREM2 cause the rare genetic disorder Nasu-Hakola disease (NHD)." (PMID 30127723, 2018). "Homozygous missense mutations in TREM2 cause Nasu-Hakola disease (NHD), an early-onset dementia." (PMID 30157425, 2018). "TREM2 was first identified as a genetic cause of PLOSL, also commonly known as Nasu-Hakola disease, which is characterized clinically by bone cysts and fractures, neuropsychiatric symptoms and dementia." (PMID 28768545, 2017). "These mice will be valuable for investigating pathogenic mechanisms of TREM2 in both LOAD and Nasu-Hakola disease." (PMID 29273078, 2017). "Interestingly, loss-of-function mutations in the DAP12 or TREM2 genes cause a rare autosomal recessive disorder called Nasu-Hakola disease (NHD) whereas heterozygous carriers of these mutations show an elevated risk to develop AD." (PMID 28877763, 2017). "Homozygous mutations in the triggering receptor expressed on myeloid cells 2 (TREM2) are known to cause polycystic lipomembranous osteodysplasia with sclerosing leukoencephalopathy, also known as Nasu-Hakola disease (NHD)." (PMID 26754172, 2016). "Perhaps most relevant to AD, SHIP1 inhibits TREM2 signaling through DAP12 in osteoclasts, dysfunction of which is another hallmark of Nasu-Hakola disease." (PMID 26438529, 2015). "In fact, patients with Nasu-Hakola disease (NHD) characterized by pre-senile dementia and bone cyst formation, harbor loss-of-function mutations in the genes encoding DAP12 and TREM-2." (PMID 25347935, 2014). "T66M, Y38C, and Q33X homozygous variants have also previously been observed in Nasu-Hakola Disease (NHD) and are strongly suspected to result in TREM2 loss-of- function." (PMID 25664220, 2014). "The Nasu-Hakola disease, a disorder affecting both brain and bone, is known to be related to the malfunctioning of TREM2 or TYROBP." (PMID 23662159, 2013). "Additionally, the TREM2 protein is reduced in the postmortem brains of individuals with ASD as well as Nasu-Hakola disease and TREM2-KO hiPSC-derived microglia demonstrated decreased phagocytosis of synaptosomes." (PMID 40185900, 2025). "Triggering receptor expressed on myeloid cells 2 (TREM2) is expressed in microglia, and its genetic variants R47H and Y38C are linked to AD, frontotemporal dementia, and Nasu-Hakola disease, which is an early onset of dementia characterized by white matter pathology." (PMID 35685772, 2022). "Nasu-Hakola disease (NHD) is a rare autosomal recessive disorder characterized by progressive presenile dementia and bone cysts, caused by variants in either TYROBP or TREM2." (PMID 31396216, 2019).
Nasu-Hakola disease (continued). "Interestingly, CLCN2 shows co-expression with TREM2 which, other than being an AD risk gene, is known to cause leukoencephalopathy in PLOSL (polycystic lipomembranous osteodysplasia with sclerosing leukoencephalopathy), also known as Nasu-Hakola disease." (PMID 29670507, 2018). "For instance, the absence of microglial response due to null mutations in TREM2 produces Nasu-Hakola disease, a rare neurodegenerative disease." (PMID 29867449, 2018). "Additionally, TREM2 or TYROBP loss of function mutations result in Nasu-Hakola disease (NHD), also known as polycystic lipomembranous osteodysplasia with sclerosing leukoencephalopathy (PLOSL), characterized by microglial activation and dementia." (PMID 29040522, 2018). "Because TREM2 and DAP12 are predominantly expressed by microglia, microglial dysfunction caused by TREM2/DAP12 impairment was assumed to be involved in the pathogenesis of Nasu-Hakola disease." (PMID 30127720, 2018). "Nonsense, missense, and splice site mutations in TREM2 and its signaling partner DAP12 have been identified as causing Nasu-Hakola disease, a rare, autosomal recessive syndrome marked by early-onset progressive dementia and osteoclast dysfunction resulting in bone cysts." (PMID 26438529, 2015). "Mutations in TREM-2 and DAP12 cause sclerotic lesions in the white matter of the central nervous system (CNS) in human polycystic lipomembranous osteodysplasia with sclerosing leukoencephalopathy (PLOSL)/Nasu-Hakola disease and cause hypomyelinosis in mice." (PMID 25187205, 2014). "Recessive mutations in both TREM2 and DAP12 produce the clinical phenotype of Nasu-Hakola disease." (PMID 23800361, 2013). "Genetic variations in TREM2 have been implicated in several neurodegenerative disorders, including AD, frontotemporal dementia (FTD), and Nasu-Hakola disease (NHD), with over 70 variants identified to date." (PMID 40247363, 2025). "However, TREM2 was first implicated in human health and disease when variants of TREM2 and its adaptor protein DAP12 were identified in families with Nasu-Hakola Disease, which is also known as polycystic lipomembranous osteodysplasia with sclerosing leukoencephalopathy." (PMID 36119485, 2022). "In addition, the homozygous TREM2 mutations that cause the frontal lobe dementia associated with Nasu-Hakola disease impair TREM2 function, locking microglia in a homeostatic, rather than phagocytic, state and produce very low CSF sTREM2 levels." (PMID 30111356, 2018). "The importance of TREM2 in the CNS was first highlighted by the discovery of Nasu-Hakola disease (NHD), a rare autosomal recessive disorder presented with an early onset dementia." (PMID 30038567, 2018). "Biallelic loss-of-function variants in TYROBP and TREM2 cause autosomal recessive presenile dementia with bone cysts known as Nasu-Hakola disease (NHD, alternatively polycystic lipomembranous osteodysplasia with sclerosing leukoencephalopathy, PLOSL)." (PMID 40301889, 2025). "Rare variants of TREM2 that cause complete lack of TREM2 expression were first reported in Nasu-Hakola disease (NHD), an autosomal recessive early-onset dementia with bone cysts." (PMID 36564824, 2022). "Although TREM2 heterozygous RDVs were reported as risk factors for AD and FTD, the biallelic rare variants were associated with a monogenic disease, Nasu-Hakola disease (NHD)." (PMID 35752680, 2022). "TREM2 mutations such as Y38C and T66M are related to a genetic disease known as Nasu-Hakola disease [NHD, polycystic lipomembranous osteodysplasia with sclerosing leukoencephalopathy (PLOSL)]." (PMID 28149270, 2016). "Nasu-Hakola disease (NHD) is a rare autosomal recessive disorder characterized by sclerosing leukoencephalopathy and multifocal bone cysts, caused by a loss-of-function mutation of either DAP12 or TREM2." (PMID 24886140, 2014).